AGO4 (argonaute RISC component 4)
Description:
Required for RNA-mediated gene silencing (RNAi). Binds to short RNAs such as microRNAs (miRNAs) and represses the translation of mRNAs which are complementary to them. Lacks endonuclease activity and does not appear to cleave target mRNAs. Also required for RNA-directed transcription and replication of the human hapatitis delta virus (HDV).
Synonyms: hAgo4; EIF2C4; KIAA1567; FLJ20033
Tractability: PROTAC: UniProt records ubiquitination sites on it; ubiquitination databases record sites on it.
Gene: Protein-coding gene on chromosome 1 (35,808,016 to 35,857,890, forward strand). Ensembl gene ENSG00000134698.
Subcellular location: Cytoplasm, P-body
Subcellular location (Human Protein Atlas): Cytoplasmic bodies; Cytosol
Pathways (Reactome):
Gene expression (Transcription): MicroRNA (miRNA) biogenesis; Post-transcriptional silencing by small RNAs; RUNX1 regulates genes involved in megakaryocyte differentiation and platelet function; Regulation of NPAS4 mRNA translation; Regulation of RUNX1 Expression and Activity; Small interfering RNA (siRNA) biogenesis; Transcriptional Regulation by VENTX
Signal Transduction: Ca2+ pathway; Competing endogenous RNAs (ceRNAs) regulate PTEN translation; Estrogen-dependent gene expression; MAPK6/MAPK4 signaling; MTOR signalling; NR1H3 & NR1H2 regulate gene expression linked to cholesterol transport and efflux; Pre-NOTCH Transcription and Translation; Regulation of PTEN mRNA translation; TGFBR3 expression
Cell-Cell communication: Regulation of CDH1 mRNA translation by microRNAs; Regulation of CDH11 mRNA translation by microRNAs
Cellular responses to stimuli: Oncogene Induced Senescence; Oxidative Stress Induced Senescence
Developmental Biology: Regulation of MITF-M-dependent genes involved in apoptosis
Disease: Nuclear events stimulated by ALK signaling in cancer
Immune System: Regulation of PD-L1(CD274) translation
Gene Ontology:
Molecular function: double-stranded RNA binding; miRNA binding; protein binding; single-stranded RNA binding; nucleic acid binding; RNA binding
Biological process: miRNA processing; miRNA-mediated gene silencing by inhibition of translation; miRNA-mediated gene silencing by mRNA destabilization; mRNA catabolic process; pre-miRNA processing; RISC complex assembly; siRNA-mediated gene silencing by mRNA destabilization; regulatory ncRNA-mediated post-transcriptional gene silencing
Cellular component: cytoplasm; cytoplasmic ribonucleoprotein granule; membrane; RISC complex; RISC-loading complex; cytosol; nucleus; P-body
Genetic constraint (gnomAD): Loss-of-function variants: 30 observed, 103.41 expected, observed/expected ratio (o/e) 0.29, 90% interval 0.22 to 0.39. The upper end of that interval is the gene's LOEUF score, 0.39, which puts it in group 1 of 6, group 1 being the genes least tolerant of losing a copy. Missense variants: 706 observed, 1,113 expected, observed/expected ratio (o/e) 0.63, 90% interval 0.6 to 0.68. Synonymous variants: 326 observed, 377.89 expected, observed/expected ratio (o/e) 0.86, 90% interval 0.79 to 0.95.
Homologues: Orthologues: chimpanzee AGO4 (100% identical), rabbit AGO4 (99% identical), mouse Ago4 (99% identical), rat Ago4 (99% identical), zebrafish ago4 (98% identical), tropical clawed frog ago4 (98% identical), guinea pig AGO4 (98% identical), macaque AGO4 (95% identical), Caenorhabditis elegans alg-3 (40% identical), Caenorhabditis elegans alg-4 (40% identical), Caenorhabditis elegans hrde-1 (25% identical), Caenorhabditis elegans wago-10 (25% identical), and 6 more. Paralogues in human: AGO1 (83% identical), AGO3 (82% identical), AGO2 (78% identical).
Diseases named in the same sentence as AGO4 in open-access papers:
AGO4 is named in the same sentence as 24 diseases in open-access papers, as found by Europe PMC text mining. Sharing a sentence is not in itself a finding about the gene and the disease. The quoted sentences say what the papers report.
viral infection (6 papers, 2015 to 2022). "In their experiments, they reported that immune cells with AGO4 deficiency and AGO4 knockout mice were significantly more susceptible to viral infections." (PMID 32503341, 2020). "It has been found that hypoxia tolerance required AGO1 and AGO4 RNA-silencing pathways, while virus infection silenced AGO1." (PMID 35891562, 2022). "It remains to be determined whether this function is virus-specific and how AGO4 expression could be increased to control viral infections." (PMID 32503341, 2020). "Excluding from the analysis enzymes that were upregulated in leaves and/or roots of the self-grafted genotypes, we can conclude that the overexpression of AGO1, AGO4 and DCL2 in the leaves of Sl-UC grafted on Sl-Ma was very likely in response to viral infection." (PMID 26496695, 2015).
gastric cancer (3 papers, 2016 to 2018). A primary or metastatic malignant neoplasm involving the stomach. "In summary, our study results showed differentially regulated lncRNAs and gastric cancer-associated genes such as EGFR, KLF4, DNMT1 and AGO4 are candidates of ceRNA network in gastric cancer." (PMID 29719612, 2018). "This study identifies the gastric cancer-associated genes such as EGFR, KLF4, DNMT1 and AGO4 as candidates of ceRNA network in gastric cancer." (PMID 29719612, 2018). "Although we found a differential expression of EGFR, FGFR2, KLF4, DNMT1 and AGO4 in gastric cancer samples, only FGFR2 overexpression was statistically significant (P = 0.0449)." (PMID 29719612, 2018). "In addition to the lncRNAs, we also profiled the expression pattern of identified candidate gastric cancer-associated genes EGFR, FGFR2, KLF4, DNMT1 and AGO4 shortlisted from the analysis of genes by relative quantification." (PMID 29719612, 2018). "The prediction identified three microRNAs (miR-21, miR-145 and miR-148a) and five gastric cancer-specific target genes (EGFR, KLF4, DNMT1 and AGO4) which also showed strong correlation with lncRNAs in regression analysis." (PMID 29719612, 2018). "Knockdown of AGO1, but not of Argonaute 2 (AGO2), Argonaute 3 (AGO3) or Argonaute 4 (AGO4), abolished the miR-558-facilitated protein and transcriptional levels of HPSE in gastric cancer cells." (PMID 27685626, 2016). "We analyzed the expression level of gastric cancer-related genes EGFR, FGFR2, KLF4, DNMT1 and AGO4 identified through bioinformatics screening by relative quantification method and observed differential expression of EGFR, FGFR2, KLF4, DNMT1 and AGO4 in tumors." (PMID 29719612, 2018).
breast carcinoma (2 papers, 2011 to 2015). "There are four argounatue (AGO) proteins in humans AGO1–4 and evaluation of alterations in AGO1–4 gene expression across breast cancer cell lines and tumor samples has shown that AGO2 is increased in ER− samples versus ER+ while there is no change in AGO1, AGO3, or AGO4." (PMID 26062653, 2015).
glioblastoma (2 papers, 2021). The most malignant astrocytic tumor (WHO grade IV). "A DNA methyltransferase 3A (DNMT3A)/AGO4 complex abolished miR-181-5p inhibition of gene expression via the cytosine methylation of miR-181-5p and resulted in an aggressive outcome of a glioblastoma multiforme (GBM)." (PMID 34068010, 2021). "In glioblastoma-derived cell lines and glioblastoma tumor samples, the methylation of mature miR-181a-5p by the DNMT3A/AGO4 complex inhibits the recognition of its target mRNA BIM, a proapoptotic gene, also known as B-cell chronic lymphocytic leukemia/lymphoma (Bcl-2)-like 11 (BCL2L11)." (PMID 34282776, 2021).
ovarian carcinoma (2 papers, 2021). A malignant neoplasm originating from the surface ovarian epithelium. "AGO4 is closely related to ovarian development in laying hens, and its mutation may induce ovarian cancer." (PMID 34828373, 2021). "In addition, differential expression of DICER1, AGO3, and AGO4 was reported in the estrogen-dependent development of the chicken female reproductive tract and hen’s ovarian cancer, suggesting that the sex-steroid hormones play an essential role in the biosynthesis of miRNAs." (PMID 33477993, 2021).
co‐infection (1 paper, 2020). "Earlier, a co‐infection of CMV was shown to compromise Ty‐1 resistance, likely due to the abrogation of AGO4 activity by the CMV 2b RNAi suppressor protein." (PMID 31756021, 2020).
endothelial dysfunction (1 paper, 2025). In vascular diseases, endothelial dysfunction is a systemic pathological state of the endothelium (the inner lining of blood vessels) and can be broadly defined as an imbalance between vasodilating and vasoconstricting substances produced by (or acting on) the endothelium. "These factors may be the main reasons for AGO4’s unique action of inducing endothelial dysfunction, but it may also be that more than one pathway is causing this dysfunction in KD or that different miRNAs are inducing different routes by attacking dissimilar AGOs." (PMID 39857904, 2025). "AGO2 and AGO4 are likely to participate in the endothelial dysfunction of children with KD, with AGO4 potentially playing a key role, while AGO1 and AGO3 appear not to participate." (PMID 39857904, 2025).
gastric tumor (1 paper, 2018). "Compared to PTENP1-AS, the GAS5 expression was predominantly upregulated in the gastric tumor samples and the expression level was comparatively higher than competing mRNA AGO4." (PMID 29719612, 2018).
influenza infection (1 paper, 2021). "AGO4 deficiency in influenza infection results in higher viral titres in vivo." (PMID 34671358, 2021).
lupus (1 paper, 2015). "In SLE, it was reported that anti-Su autoantibodies, which were usually found in lupus patients, could recognize the catalytic enzyme in miRNA pathways (Ago1, Ago2, Ago3, Ago4 and Dicer), which indicated the possible mutual relationship between miRNA and the pathogenesis of SLE." (PMID 25927578, 2015).
melanoma (1 paper, 2016). A malignant, usually aggressive tumor composed of atypical, neoplastic melanocytes. "Next, we determined the mRNA expression of AGO1, AGO2, AGO3 and AGO4 in different melanoma cell lines derived from primary tumors and metastases and in non-melanoma tumor cell lines." (PMID 27518285, 2016). "The AGO protein expression patterns relative to each other were similar for AGO2 and AGO4 (47–55% for AGO2; 7–10% for AGO4 of the total AGO protein pool) in the melanoma cell lines." (PMID 27518285, 2016).
neuroblastoma (1 paper, 2021). Neuroblastoma (NB) is the most common solid, extracranial childhood tumor. "Such patterns of AGO protein expression implies crucial importance of AGO4-mediated regulation of gene expression in the differentiation of neuroblastoma cells." (PMID 33668654, 2021).
prostate carcinoma (1 paper, 2014). A carcinoma that arises from epithelial cells of the prostate gland. "EIF2C2 (AGO2) transcript presents contrasting regulation depending on the cell line whereas EIF2C4 (AGO4) appears to be up-regulated in two other cell lines (HUVEC and prostate cancer at 48 h and 72 h of hypoxia, respectively." (PMID 24517586, 2014).
infection (14 papers, 2011 to 2022). The state of being infected such as from the introduction of a foreign agent such as serum, vaccine, antigenic substance or organism. "It was reported that AGO4 mainly combated the aggression of DNA viruses through modulating RdDM, as reported that ago4 mutants was susceptible to the infection of BCTV due to the diminished hypermethylation on BCTV genome." (PMID 35216025, 2022). "Our finding that key regulators of TGS (AGO4) were altered during acute infection implies that the altered TGS-mediated pathway could cause broad-range changes in host gene regulation." (PMID 31051010, 2019). "We then compared the percentage of cytosine methylation in the intergenic region in local infections with the V2 null mutant TYLCV in basal conditions or upon AGO4 silencing." (PMID 33064077, 2020). "At later stages of infection, RdDM genes encoding DCL3, and the executors AGO4 and AGO9 as well as the downstream effector MET1 were down‐regulated." (PMID 31274236, 2019). "In contrast to ToLCNDV infection, genes associated with the TGS machinery (such as AGO4, AGO7, DCL3) were significantly down-regulated in leaves recovered from ToLCGV infection." (PMID 29432546, 2018). "(2013) showed that Pst DC3000 infection of Arabidopsis represses RdDM genes, such as AGO4, AGO6, NRPD2, and RDR1, which offers a plausible explanation as to why Pst DC3000 induces DNA hypo‐methylation in Arabidopsis." (PMID 27341062, 2016). "To test whether this strategy is also employed by V2, we immunoprecipitated 3xFLAG-NbAGO4-1 co-expressed with wild-type or V2 null mutant TYLCV in local infection assays in N. benthamiana, and visualized AGO4-bound vsiRNA by sRNA northern blotting." (PMID 33064077, 2020). "(B) Percentage of methylated cytosines in the intergenic region (IR) of TYLCV in local infection assays with the V2 null mutant TYLCV (TYLCV-V2null) in AGO4-silenced (TRV-NbAGO4) or control (TRV-EV) N. benthamiana plants at 4 dpi, as detected by bisulfite sequencing." (PMID 33064077, 2020). "Conversely, argonaute protein 2 (AGO2) that together with AGO4 are the effectors in the RNAi pathway against the infection of RNA viruses showed a moderate up-regulation only in Ma (FC = 1.54; RQ = 0.94) and in all graft combinations (FC between 1.39 and 1.68; RQ between 1.4 and 2.05)." (PMID 32054920, 2020). "AGO4, SNX9, SCD were also downregulated after infection with MA08." (PMID 34671358, 2021). "Next, we sought out to test whether knock-down of AGO4 could partially complement the lack of V2 during the TYLCV infection." (PMID 33064077, 2020).
cancer (6 papers, 2010 to 2022). A tumor composed of atypical neoplastic, often pleomorphic cells that invade other tissues. "Other interesting examples included AGO4, LIN28A and SMAD2 overmutated in BLCA (an otherwise extremely low-mutation cancer with no mutations in other genes); LIN28B overmutated in SKCM; PRKRA overmutated in OV; and DDX5 overmutated in BRCA and KIRP." (PMID 33406242, 2021).
tumor (6 papers, 2007 to 2021). "This indicates that wildtype plants restrict tumor growth by changes in the methylation pattern of cellular genes which are altered in ddc and ago4 mutants." (PMID 23408907, 2013). "A similar difference in tumor growth was found between wildtype plants and the ago4 mutant, which is impaired in RNA-dependent methylation processes." (PMID 23408907, 2013). "Hence, AGO4 may contribute to neoplasia formation via promotion of miRNA cytosine methylation, and thus inhibition of tumor suppressor miRNAs." (PMID 33668654, 2021). "As we found many changes in miRNA expression across the five clinical tumor subtypes we had defined above, we asked whether DICER1, DROSHA, DGCR8, AGO1, AGO2, AGO3 or AGO4 expression differs among these subgroups." (PMID 17922911, 2007).
bacterial infection (2 papers, 2010 to 2021). "Recent work by Agorio and Vera (2007) showed the role of AGO4 in the process of resistance of Arabidopsis to Pseudomonas syringae; these scientists found that ago4 was sensitive to bacterial infection." (PMID 20209086, 2010). "In addition, expression of AGO4 is reduced by bacterial infection or after treatment with the MAMP flg22, thus implying a role of AGO4 in the antibacterial defence response of plants." (PMID 33073913, 2021).
AGO4 also shares sentences with these, for which no sentence is quoted: colon cancer (1 paper); developmental delay (1); glioma (1); Insulin resistance (1); Kawasaki disease (1); liver disease (1); Pheochromocytoma and Paraganglioma (1).